CD4 (CD4 molecule)
Diseases named in the same sentence as CD4 in open-access papers (continued):
Sharing a sentence is not in itself a finding about the gene and the disease.
myeloma (152 papers, 2004 to 2025). "Myeloma is associated with relatively high CD4+ T-cell counts in PWH and typically presents with an immunoglobulin G (IgG) paraprotein, implying a possible relationship between myeloma and an IgG response to HIV antigens." (PMID 38601746, 2024). "Cohen first discovered that B cell maturation antigen-specific chimeric antigen receptor (CAR) T cells reponse were positively associated with higher premanufacturing CD4/CD8 T cell ratio in multiple myeloma." (PMID 37063862, 2023). "This possibility is virtually excluded in the MOPC315 model since CD4+ T cells recognize a somatically mutated tumor-specific antigen unique to MOPC315 myeloma cells." (PMID 24782871, 2014). "In Id-specific TCR-transgenic mice, tolerance in the presence of the growing myeloma is associated with deletion of tumor-specific thymocytes and peripheral CD4+ T cells." (PMID 23144743, 2012). "Furthermore, studies have found that a lower CD4+/CD8+ ratio at diagnosis is linked to poor prognosis in patients with multiple myeloma and Waldenström’s macroglobulinemia." (PMID 41244913, 2025). "Similarly, decreased LAG3 expression on CD4+Foxp3+ T cells was associated with significantly longer PFS in patients with multiple myeloma." (PMID 39456740, 2024). "We analyzed a variety of clinical factors (gender, age, β2-MG, type of light chain, ISS stage, plasma cell number in bone marrow, peak concentration of IL-6 and CRP, and minimum value of CD4/CD8) that may be associated with CRS in patients with multiple myeloma separately." (PMID 33708205, 2021). "The expression levels of both BDNF and phospho‐TBK1 were elevated in the CD4+ T cells from AL amyloidosis patients compared to myeloma patients." (PMID 40977494, 2025). "For instance, in the CD4+ T cells in samples from patients with myeloma or AL amyloidosis, six analytes (phospho‐p38 MAPK, phospho‐RIP, phospho‐Shp2, phospho‐SQST, phospho‐STING, and phospho‐ULK1) demonstrated high levels of bivariate correlations." (PMID 40977494, 2025). "Treatment with daratumumab or isatuximab can rapidly deplete CD38+ regulatory T cells (Tregs), myeloid-derived suppressor cells (MDSCs), and Bregs and is associated with clonal expansion of CD4+ and CD8+ T cells in myeloma patients." (PMID 41567224, 2025). "Logistic regression and ROC analysis showed that BDNF in CD4+ T cells and heme oxygenase 1 in monocytes significantly distinguished between patients with myeloma versus patients with AL amyloidosis (AUC = 0.75)." (PMID 40977494, 2025). "BDNF, calmodulin, and phospho‐TBK1 levels were decreased in CD4+ T cells from AL amyloidosis patients compared to myeloma patients." (PMID 40977494, 2025). "Conversely, we found bivariate correlations in the cells from AL amyloidosis patients that were apparent in the CD4+ T cells from the myeloma patients." (PMID 40977494, 2025). "Tfh/CD4+ were positively correlated with the proportion of myeloma cells in the BM and PB samples (r = 0.592, P = 0.002 and r = 0.510, P = 0.010 respectively), and showed a strong correlation between the BM and PB samples (r = 0.6559, P = 0.0095)." (PMID 39324138, 2024). "Patients with multiple myeloma showed CD4+ T/CD8+ T ratios decrease along with cancer development by CyTOF." (PMID 39877263, 2024). "Blocking immunosurveillance of B‐cell lymphoma and myeloma via CD4 T cell is a suggestive pathophysiological pathway due to the increased risk of cancer in long‐term use of fingolimod in patients." (PMID 37113637, 2023). "Vaccination resulted in all evaluable patientsdemonstrated at least a twofold expansion of myeloma specific CD4+ and/or CD8+ T cells." (PMID 37275861, 2023). "On the other hand, PVd treatment decreased the number CD4+ cells expressing PD-1, enhancing the overall anti-myeloma response, and subsequently PFS was improved." (PMID 38111533, 2023). "On one hand, B7-H2 expressing myeloma cells induced CD4+ T cells to proliferate and produce soluble factors which stimulate myeloma cell proliferation." (PMID 36922519, 2023).
myeloma (continued). "With the unbiased t-SNE plot analysis, it was visible that γδT cells were more abundant in myeloma patients, TCRγδ being co-expressed in part with CD4, CD8 or in the compartment of Tfh cells by co-expressing CXCR5." (PMID 37187728, 2023). "We used conventional expert‐gating to define the major cell populations (T cells, CD45+CD3+CD56−, DCs: CD45+CD3−CD19−CD56−HLA‐DR+CD4+ and myeloma cells, CD45−CD38hi) then subsequent FLOWSOM clustering to define the downstream subsets." (PMID 38034081, 2023). "A decrease in CD4/CD8 ratio has previously been described in patients with multiple myeloma after treatment with daratumumab and bortezomib." (PMID 36874402, 2022). "Shao and colleagues confirmed that EXSMs from multiple myeloma cell lines in humans inhibit CD4+ proliferation and promote proliferation and TGF-β secretion by Tregs." (PMID 36077229, 2022). "Previous studies have found patients with multiple myeloma have lower CD4+ T/CD8+ T ratios relative to healthy donors and these ratios are further decreased in ISS stage 3 versus ISS stage 1 patients." (PMID 36969740, 2022). "In some investigations, either elevated absolute Treg numbers or an imbalance in the ratio of Treg to TH17 or CD4 effector cells are correlated with myeloma progression and impaired clinical outcome." (PMID 35159220, 2022). "Another integrative bioinformatics analysis revealed that CDKN2A shows a significant correlation with immune signatures in multiple myeloma, including CD4+ regulatory T cells, T cell exhaustion, and neutrophils." (PMID 35937995, 2022). "Even though fratricide occurred during Luc90-CAR-T production, Luc90-CAR-T composed of mostly CD4 + cells demonstrated efficacy in our mouse model of myeloma." (PMID 35422095, 2022). "Specifically, the percentage of CD4+ T cells was significantly reduced in bone marrow of patients with multiple myeloma, leading to altered CD4+ T/CD8+ T ratio." (PMID 36969740, 2022). "Among patients, the relative defect in secretory effector function of CD4 T cells was more pronounced at myeloma relapse (as seen in declined Th1/Treg and Th17/Treg cell rates)." (PMID 34502204, 2021). "5TMM has also been used to examine immunomodulatory myeloma treatments at the preclinical level; e.g., investigators demonstrated that CD4 T cells were vital for lenalidomide’s activity, while NK, B or CD8 T cells were not." (PMID 34149703, 2021). "AR‐42 treatment reduced IL‐6RA and GP130 mRNA similar to reports of AR‐42 activity in multiple myeloma cells and the activity of pan‐HDACis in naïve CD4+ T cells." (PMID 31930715, 2020). "In untreated myeloma patients, CD4:CD8 ratios were significantly decreased to 2.54 as compared to healthy donors (p=0.030), however, the ratios were still positive and significantly higher as compared to patients after autoSCT (p=0.023)." (PMID 33363008, 2020). "M1 polarization of TAMs in vivo upon interaction with tumor antigen specific CD4+ T cells has also been demonstrated in a murine multiple myeloma model based on TCR transgenic SCID mice." (PMID 30853959, 2019). "LB-LILRB1-1I specific CD4 T-cells were incubated with myeloma cell-lines UM-6, UM-3, RPMI8226, and U266 transduced with HLA-DQB1*06:02." (PMID 30619360, 2018). "LB-ACBA5-1R specific CD4 T-cells were incubated with myeloma cell-lines UM-6 and RPMI8226 transduced with HLA-DRB1*11:01." (PMID 30619360, 2018). "To elucidate the molecular basis of CD4+ T-cell-mediated tumor rejection, we utilized a murine model of multiple myeloma, in which the T cells recognize a secreted tumor neoantigen." (PMID 30083157, 2018). "We investigated dynamics of CD4+FOXP3+ T cell recovery following the high-dose chemotherapy (HDC) with autologous hematopoietic stem cell transplantation (auto-HSCT) in multiple myeloma (MM) patients." (PMID 29930767, 2018).
myeloma (continued). "The study performed by Corthay and colleagues also comprehensively characterized the mechanism by which MHC class II-negative myeloma cells were identified and eliminated by CD4 T cells." (PMID 29032503, 2018). "We have previously demonstrated that CD4+ T cells reactive against a secreted myeloma protein tumor antigen can mediate protection against tumor development upon challenge with MOPC315 myeloma cells." (PMID 30083157, 2018). "There was a trend towards a lower expression of KLF6-SV1 in CD4 T cells of myeloma patients as compared to CD4 T cells of CLL patients (p = 0.09) but not compared to healthy donors." (PMID 29432497, 2018). "Further, we tried to assess a possible direct impact of BM myeloma plasma cells (PCs) on the counts of peripheral blood (PB) CD4+FOXP3+ T cells." (PMID 29930767, 2018). "As the myeloma burden progresses, percentages of PD-1+CD4+ and CD8+ T cells correspondingly increase." (PMID 28642819, 2017). "An IgG-based BCMA-T cell bispecific antibody (EM801) also increased CD3+ T cell/myeloma cell crosslinking, followed by CD4+/CD8+ T cell activation, and secretion of interferon-gamma, granzyme B, and perforin A." (PMID 31548533, 2017). "In contrast the frequency of CCR4-expressing CD4+ T cells in BM was substantially increased in patients with myeloma to an average expression of 20% of the CD4+ T cell pool (**p = < 0.01)." (PMID 28389623, 2017). "First, significantly increased levels of CD38 were shown on the cell membrane of Tregs (CD4+CD25highFoxp3+) and myeloma cells when compared with conventional T (Tcon, CD4+CD25−) cells containing the majority of effector T cells." (PMID 31548533, 2017). "The potential importance of CD4+ TH17 cells in patients with multiple myeloma is an area of considerable interest and an increase in the frequency of such cells within the bone marrow has been reported." (PMID 28389623, 2017). "To investigate the effect of chaetocin-treated dying myeloma cells on the induced antitumor response against myeloma cells, we evaluated the T cell polarization capacity of CD4+-naïve T cells by stimulation of the DCs." (PMID 28512265, 2017). "During the third rebound the individual was treated with thalidomide for relapse of multiple myeloma and his CD4+ T cell count was at its lowest (around 200 cells /ul)." (PMID 27403738, 2016). "In brief, both, CD3+CD4+ as well as CD3+CD8+ T cells exhibited enhanced expression of PD-1 in PB as well as BM of myeloma patients." (PMID 27809856, 2016). "Elevated proportions of Th17 cells have been identified in the total CD4+ T cell populations in several different human solid tumors and hematological malignancies including ovarian, prostate carcinomas, multiple myeloma, and acute myeloid leukemia." (PMID 27176825, 2016). "As myeloma burden progressed, the percentages of bone marrow-derived PD-1+ CD4 and CD8 T cells increased to 40-70% and 30-50%, respectively." (PMID 25614821, 2015). "We clearly demonstrate CD4+ cells against survivin are circulating within healthy individuals and myeloma patients." (PMID 25992291, 2015). "In healthy donors and myeloma patients we have quantified the peripheral blood CD4+ T cell precursor frequency reactive against survivin." (PMID 25992291, 2015). "Myeloma patients had a significantly lower precursor frequency of survivin reactive CD4+CD25- cells (range 0% to 2.2x10-3%) compared to healthy donors (range 1.1x10-3 to 8.4x10-3%)." (PMID 25992291, 2015). "Taken together, these data clearly showed that lenalidomide enhances the type I anti-myeloma CD4+ and CD8+ T cell responses in vivo." (PMID 26447613, 2015). "Multiple myeloma patients (range 0% to 2.2x10-3%, n=12) had fewer survivin reactive CD4+CD25- T cells than healthy blood donors (range 1.1x10-3 to 8.4x10-3%, n=10), p = 0.021." (PMID 25992291, 2015).
myeloma (continued). "It was previously shown that myeloma patients can harbor CD4 and CD8 T cells reactive against survivin, however this required multiple stimulation and expansion steps, precluding a precise quantification of the circulating T cell precursor frequency." (PMID 25992291, 2015). "In order to better understand the survivin specific immune response and optimize vaccination strategies against myeloma, we sought to characterize the survivin specific CD4+ T cell response using survivin derived peptide pools." (PMID 25992291, 2015). "On day 21 after myeloma inoculation, CD4 T cells were harvested from the spleen and purified by immunomagnetic cell sorting." (PMID 25614821, 2015). "Similar to healthy donors, myeloma patient CD4+CD25- T cells expand in response to DC:survivin stimulation." (PMID 25992291, 2015). "We tested the ability of a full length survivin protein vaccine to expand myeloma CD4+CD25- T cells that are reactive against survivin peptide pool loaded autologous DCs." (PMID 25992291, 2015). "We evaluated the precursor frequency of survivin reactive CD4 T cells in the peripheral blood of 10 consecutive healthy donors and 12 consecutive multiple myeloma patients." (PMID 25992291, 2015). "We observed increased expression of TIM-3, LAG-3, CTLA4, and 2B4 on both CD8 and CD4 T cells in myeloma-bearing mice, and anti-myeloma synergy occurred when the PD-1/PD-L1 axis was blocked in combination with blocking TIM-3, LAG-3, or CTLA4." (PMID 25614821, 2015). "We have, for the first time, quantified the circulating, CD4+ precursor frequency against survivin in healthy donors and myeloma patients." (PMID 25992291, 2015). "The survivin reactive frequency was determined before and after myeloma patient CD4+CD25- T cells were co-cultured with autologous DCs infected with Ad-ms." (PMID 25992291, 2015). "Myeloma patients have decreased survivin specific CD4+ cells compared to healthy donors, yet CD4+ responses against common viral antigens were similar." (PMID 25992291, 2015). "At 72 hours, myeloma patients CD4+CD25- T cell proliferation and IFN-gamma release in response to DC:survivin was not different from healthy donors." (PMID 25992291, 2015). "We aimed to explore the role of CD4+CD25+ cells in the pathogenesis of multiple myeloma (MM) related renal impairment (RI)." (PMID 26564056, 2015). "Healthy donors and myeloma patients’ CD4+CD25- T cells exhibited a proliferative and IFN-gamma response against survivin peptides loaded onto autologous dendritic cells." (PMID 25992291, 2015). "A vaccine strategy to increase these CD4+ T cells in patients would be the ideal strategy to evaluate their activity against myeloma." (PMID 25992291, 2015). "Survivin expression in myeloma patients’ tumors correlates with decreased survivin reactive CD4+ T cells." (PMID 25992291, 2015). "Rats were immunized with CD4+ T cells prepared from fresh healthy human peripheral blood mononuclear cells (PBMCs), and spleen cells were fused with myeloma cells." (PMID 25400923, 2014). "Within CD4 T cells, the results revealed 6 myeloma-reactive Vβ families (2, 3, 5.1, 5.2, 8.3, 11) and 5 alloreactive Vβ families (5.1, 5.2, 11, 15, 18)." (PMID 25415267, 2014). "Vβ families 5.1., 5.2 and 11 showed expansion both in the anti-myeloma and allogeneic settings, suggesting overlapping responses of these CD4 T-cell populations." (PMID 25415267, 2014). "A weak cytotoxicity that was greatly augmented by addition of high amounts of myeloma protein was observed when Id-specific CD4+ T cells were co-cultured with MHC-compatible spleen cells from BALB/c (H-2d) MHC IINEG MOPC315." (PMID 24782871, 2014). "Taken together, in the absence of SH2D2A, TCR-transgenic mice are better protected from transplanted myeloma, which correlates with reduced central deletion of tumor-specific SP CD4+ thymocytes in tumor-free mice." (PMID 23144743, 2012).
myeloma (continued). "It has previously been observed that the tumor protective effect of Id-specific TCR transgenic CD4+ T cells can be partially overcome by injection of a greater number of myeloma cells, leading to tumor development in 60–80 % of wild-type TCR-transgenic mice." (PMID 23144743, 2012). "To explore the effect of SH2D2A deficiency in a more physiological context we used a well-characterized TCR-transgenic model for CD4+ T cell mediated resistance to the MOPC315 mouse myeloma." (PMID 23144743, 2012). "Such Id-specific TCR transgenic BALB/c mice are enriched for CD4+ T cells expressing TCRs recognizing a myeloma-derived Id peptide from the variable region of the MOPC315 myeloma secreted immunoglobulin light chain, presented on MHC class II I-Ed." (PMID 23144743, 2012). "For examples, infusion of myeloid DCs and systemic administration of IL-2 have been shown to induce and expand CD4+FoxP3+ Tregs in myeloma and renal cancer patients." (PMID 21106069, 2010). "One possible explanation might be that a low CD4+ cell count is a risk factor for PJP even in HIV-negative patients and that CD4+ cell counts decrease with each line of myeloma therapy." (PMID 38123879, 2024). "In addition, in another study, the reconstituted bone marrow-residing CD4+CD25+FOXP3+ Treg of the myeloma patients after allogeneic stem cell transplantation consisted preferably of CD45RA−CCR7- memory T cells." (PMID 39335199, 2024). "Furthermore, HDs were found to have a significantly higher CD4/CD8 T-cell ratio than patients with late relapse multiple myeloma." (PMID 36874402, 2022). "However, CD4/CD8 ratio was significantly lower in the late relapsed multiple myeloma group compared with HDs (0.15 vs. 1.43 ± 0.1, P < 0.005)." (PMID 36874402, 2022). "The balance between anti-tumor activity by cytotoxic CD8+ T cells and immunosuppression by CD4+ Treg cells is considered a key driver of progression in myeloma from the preliminary monoclonal gammopathy of undetermined significance (MGUS) to MM by many reports." (PMID 35159220, 2022). "Characterization of the TCR repertoire in LTR revealed a higher involvement of the CD8+ T cells compared to CD4+ T cells, which is consistent with immunological studies in myeloma patients achieving long-term disease control showing increased frequencies of CD8+ T cells." (PMID 35865461, 2022). "In contrast, patients with untreated newly diagnosed multiple myeloma had a similar CD4/CD8 ratio to HDs suggesting that prior antimyeloma treatment may have an impact on the CD4/CD8 ratio." (PMID 36874402, 2022). "In particular, active treatment with anti-CD38 monoclonal antibodies or anti-BCMA bispecific antibodies was associated with decreased CD4+ T cell responses, while patients treated with anti-BCMA CAR T cells mounted similar CD4+ T cell responses compared to myeloma patients receiving other therapies." (PMID 35214642, 2022). "Furthermore, we sought to investigate the relationship between clinical features and immune cell composition of patients with multiple myeloma by examining the ratio of CD4+/CD8+ T cells of patients at different disease stages." (PMID 36969740, 2022). "CD4+ T cells were found to induce macrophage-mediated tumor rejection in myeloma." (PMID 34283809, 2021). "Importantly, together with its parental line, MOPC315.BM has made major contributions to our appreciation of CD4 T cell responses in immunosurveillance and -therapy of myeloma, briefly summarized below." (PMID 34149703, 2021). "Nonetheless, myeloma CD4 T cells had significantly defective levels of all studied checkpoints, primarily at myeloma diagnosis, which may be insufficient for appropriate blockade with therapeutic inhibitors." (PMID 34502204, 2021). "Our finding of a negative correlation of enriched PB Treg cells with MM stage may correspond with their role in systemic CD4 T cell senescence supporting myeloma growth." (PMID 34502204, 2021).